LPL (lipoprotein lipase)
Diseases named in the same sentence as LPL in open-access papers (continued):
Sharing a sentence is not in itself a finding about the gene and the disease.
Insulin resistance (continued). "Conversely, ANGPTL6 had been shown to negatively correlate with obesity and insulin resistance, alongside a marked increase in energy expenditure, in a manner independent of lipoprotein lipase and lipid metabolism regulation." (PMID 31396158, 2019). "Our results indicate that liver LPL has no physiological or pathophysiological effects on liver TG content and insulin resistance." (PMID 27234787, 2016). "Furthermore, we show that the LPL and SPARC promoters are enriched for Sp1 and O-GlcNAc modified proteins during insulin resistance in adipocytes." (PMID 25657638, 2014). "Recent evidence has shown that plasma LPL has significant correlation with insulin sensitivity but negative correlation with insulin resistance and fasting insulin sensitive index." (PMID 24086538, 2013). "LPL activity is usually affected by insulin resistance, diabetes and obesity, although the mechanisms are not fully resolved." (PMID 23186339, 2012). "In order to investigate TG intolerance caused by a variety of factors including heterozygous LPL-deficiency, insulin resistance, noninsulin-dependent diabetes mellitus (NIDDM), and ApoE isoforms we determined ApoE genotypes, and HL and LPL activities." (PMID 21609439, 2011). "c) Further, elevated plasma levels of ApoCIII, an inhibitor of LPL, are found in people with type 2 diabetes and non-diabetic insulin resistance, which may also be a factor in the slowed chylomicron catabolism." (PMID 38303975, 2023). "Our study findings indicate that hepatic LPL overexpression can ameliorate HFD-induced lipid accumulation in the liver without altering the systemic levels of TG and free fatty acids, leading to improvement in glucose tolerance, fasting blood glucose, and insulin resistance, as assessed by HOMA-IR." (PMID 36099304, 2022). "Therefore, in this study, we investigated whether LPL inhibition affects dyslipidemia and HDL particle size distributions in Western diet (WD)-fed db/db mice by analyzing the lipid profile, insulin resistance, and HDL subclasses of the mice." (PMID 31234537, 2019). "Indeed, the removal of TAG across adipose tissue was found to be impaired in obesity, insulin resistance and T2DM due to a reduced insulin-mediated stimulation of lipoprotein lipase (LPL) activity, suggesting less efficient removal of dietary lipids by adipose tissue in these subjects." (PMID 30234122, 2018). "Additionally, insulin resistance seems to inhibit LPL activity in whites but not in AA." (PMID 38279305, 2024). "Previous studies have confirmed that NEFA, VLDL, and high-density lipoprotein-cholesterol levels are significantly higher in obese insulin resistant horses than in lean horses without insulin resistance, which might be related to increased lipoprotein lipase activity." (PMID 36290249, 2022). "Compared to non-HIV controls, ALD-naïve PLH were associated with lower HDL-C, LPL, and higher HOMA-β, even with lower incidence of hypertension.Compared to non-HIV controls, PLH have insulin resistance reflected by low plasma HDL-C and serum LPL." (PMID 41156460, 2025). "TG levels correlate positively with insulin resistance in nondiabetic individuals and high fasting TG are normally driven by increased VLDL-TG secretion and/or compromised hydrolysis of TG by LPL." (PMID 37461091, 2023). "In this sense, we have found an upregulation of different genes related to hypoxia regardless of the degree of insulin resistance, such as ANGPTL4, LPL, S100A8, SLC11A2, HBB, HBA2, and HBD." (PMID 35625760, 2022). "In people with insulin resistance, insulin fails to effectively suppress the apolipoprotein C-III (ApoC-III), which is one of the most potent inhibitors of LPL, which inhibits LPL action in peripheral tissues and favors hepatic uptake of TG-rich chylomicron debris." (PMID 41441034, 2025).
Insulin resistance (continued). "Regardless of insulin resistance, the two groups of women with morbid obesity showed upregulation of LYPD8 and downregulation of a greater number of genes, such as REG1B, GKN2, LPL, PNLIPRP2, FKBP5, and CD86, that are related to responses to bacterial stimuli and antimicrobial activity." (PMID 35625760, 2022). "Although the effect of CLW on hepatic insulin resistance has not been previously examined, some studies have demonstrated that CLW reduced hepatic steatosis from chronic alcohol consumption and it decreases hepatic lipid accumulation by increasing hepatic and lipoprotein lipase activity." (PMID 29104217, 2017).
Obesity (260 papers, 2004 to 2026). Accumulation of substantial excess body fat. "The current study reported an association between the intronic variant rs8176337 of the LPL gene locus with obesity, as well as both rs303 and rs304 with TC and LDL." (PMID 40806414, 2025). "This is caused by the relatively reduced insulin-sensitive lipoprotein lipase activity in obesity, which leads to a decrease in HDL-C." (PMID 39981087, 2025). "As noted in the Introduction, an earlier study reported that a deficiency of LPL in neurons was associated with obesity in mice." (PMID 41031889, 2025). "Insulin sensitivity and LPL expression are also linked to another factor which can be altered in obesity: the prevalence of the different types of fibers in skeletal muscle." (PMID 38674801, 2024). "In this regard, tissue or cell-specific manipulation of LPL offers promise to overcome the cardiac complications associated with obesity and diabetes." (PMID 39081272, 2024). "Several SNPs located within the coding region of the gene encoding LpL (LpL gene) have been associated with diseases and conditions such as atherosclerosis, obesity, dyslipidemia, and Alzheimer’s disease." (PMID 38507115, 2024). "Elevated triglycerides (TGs) and a reduction in lipoprotein lipase (LPL) expression, two hallmarks of obesity, have been linked with the upregulation of sodium-coupled neutral amino acid transporter 2 (SNAT2) in a mTORC1-dependent manner." (PMID 38892329, 2024). "LPL variants have also been shown to significantly contribute to dyslipidemia, being associated with several conditions including obesity, metabolic syndrome, and atherosclerosis." (PMID 38997780, 2024). "Pre‐heparin plasma or serum LPL concentrations were reduced in LPL‐deficient individuals, and they have been used for evaluation of patients with diabetes and obesity." (PMID 37448184, 2023). "The genotype of the patients with the polymorphism rs328 of LPL must be taken into account during the prognosis of obesity and the development of its complications in children and adolescents." (PMID 37901192, 2023). "LPL, the third most frequently selected protein, is also associated with obesity and other metabolic disorders related to energy balance, insulin action and body weight regulation." (PMID 37329449, 2023). "In T2DM, LPL dysfunction or deficiency is commonly observed and is associated with atherosclerosis, Alzheimer's disease, obesity, and dyslipidemia." (PMID 36605456, 2023). "These mutations cause defective apolipoprotein E, protein phosphatase 1 like protein, lipoprotein lipase, and lactamase b, respectively, that are strongly associated with obesity." (PMID 35388304, 2022). "Abnormalities in lipid metabolism have been linked to the development of obesity, and lipoprotein lipase (LPL), a key enzyme in lipid metabolism, contributes to the development of obesity through its role in the partitioning of lipids to different tissues." (PMID 35807893, 2022). "The presence of precipitating factors such as age, obesity, pregnancy, hyperinsulinemia, and lipid-raising drugs would contribute to the phenotypic expression of heterozygous LPL deficiency." (PMID 36061186, 2022). "LPL was chosen as one of the candidate genes for the present nutrigenetic study, given that significant associations between LPL SNPs and obesity traits have been reported by previous studies in addition to their association with lipid traits." (PMID 35807893, 2022). "Increased risk of common obesity (2.73-fold increase) among carriers of the minor allele of LPL rs1800590 was also observed in Northern Indians." (PMID 35807893, 2022). "Sex-specific parental effects were also observed; variants at ANGPTL3/DOCK7 showed POE on lipid traits and obesity in daughters only, while those at LPL and TMEM57 showed POE on lipid traits in sons." (PMID 35052431, 2021).
Obesity (continued). "Specifically, mice with neuronal LPL deficiency develop obesity by six months of age and a specific PUFA deficiency associated with neurobehavioral abnormalities." (PMID 32998280, 2020). "In humans, LPL is a candidate gene for obesity, based on the function of the protein encoded by this gene to induce absorption of fatty acids across the cell walls of tissues." (PMID 32574225, 2020). "Here, we showed that mice with neuronal LPL deficiency and obesity showed improvements in glucose tolerance with aging." (PMID 32998280, 2020). "Further research selectively targeting ATM genes confirmed their definitive role in obesity-associated metabolic disorders and inflammation by displaying an altered lipid and glucose metabolism as evidenced in lipoprotein lipase (LPL) and TNFα-depleted ATMs." (PMID 32752107, 2020). "For children, GH is secreted during sleep and promotes body height and inhibits the lipoprotein lipase activity of adipose tissue, which can reduce the risk of overweight/obesity." (PMID 29693616, 2018). "Among these we found rs328 in the LPL gene, coding for lipoprotein lipase, associated with T2D and obesity simultaneously." (PMID 30126146, 2018). "It is further implicated in the cellular release of lipoprotein lipase (LPL) and is linked to obesity and glucose tolerance." (PMID 28265003, 2017). "The LPL activity is implicated as a determinant of body composition, as well as development of obesity." (PMID 28173868, 2017). "For instance, lipoprotein lipase is an obesity susceptibility factor showing an inverse relationship between its activity and obesity-related traits in humans." (PMID 29259680, 2016). "In association with the elevation of serum TGs in obesity, LPL expression in WAT was remarkably decreased in ob/ob mice compared with lean mice." (PMID 26268630, 2015). "Dysfunction of LPL protein increased the susceptibility for developing several common diseases, including atherosclerosis and obesity." (PMID 25612568, 2015). "The interaction of G Allele of ApoA5 c.56C>G polymorphism with LPL polymorphism to heighten the genetic susceptibility to obesity have also been reported." (PMID 24708648, 2014). "Brain LPL expression is reportedly regulated by nutritional and hormonal factors, and its deficiency modifies energy balance and obesity in vivo." (PMID 24004859, 2013). "In literature, correlation between LPL polymorphisms and obesity has remained controversial; however, we found evidence of this association in our study." (PMID 19804633, 2009). "WHR (>0.9 -M, 0.85 - F) was found to be a good indicator or the risk for obesity among heterozygous and homozygous subjects for LPL genotype." (PMID 19804633, 2009). "Background/Objectives: Variants in the lipoprotein lipase (LPL) gene have been associated with lipid level variability and obesity; however, their role in energy homeostasis remains unclear." (PMID 41598432, 2026). "We hypothesized that this reduction likely decreased ANGPTL4 expression levels, thereby increasing LPL activity, accelerating lipid metabolism, and reducing the risk of obesity." (PMID 41394914, 2025). "Sequence analysis employing Sanger sequencing of the LPL gene locus across different populations has revealed novel and common variants associated with an increased risk of developing dyslipidemia and metabolic disorders including obesity." (PMID 40806414, 2025). "However, it is still unclear how the genetic variants of one of the key enzymes in lipid transport, lipoprotein lipase (LPL), are associated with the endocrine function of mesenchymal tissues in obesity." (PMID 37901192, 2023).
Obesity (continued). "Thus, we conclude that the polymorphism rs328 of the lipoprotein lipase gene is accompanied by the changes in hormones, adipokines, and myokines levels in the blood of children and adolescents with obesity in gender-dependent manner." (PMID 37901192, 2023). "The current study was aimed at the investigation of the LPL rs328 gene variant association with adipokines and myokines levels, as well as lipid metabolism indices in the blood of children and adolescents of both genders with obesity." (PMID 37901192, 2023). "Moreover, it has been shown that propionate increases lipoprotein lipase’s expression and reduces obesity-associated inflammation." (PMID 37110374, 2023). "Obesity is also associated with impaired lipoprotein lipase-mediated lipolysis." (PMID 36009364, 2022). "CETP and LPL SNPs have also been associated with obesity-related traits." (PMID 35807893, 2022). "Recently, it has been proven that polyphenols could regulate the activity of LPL and then ameliorate obesity and its associated ailments." (PMID 35885328, 2022). "Our results suggest that microbial alteration associated to obesity could stimulate Fiaf expression, potentiating the inhibition of LPL and therefore, increasing the circulating levels of DG, specifically the DG 34:2." (PMID 33670496, 2021). "However, LPL can promote the uptake and storage of free fatty acids by fat cells, which is one of the critical factors leading to obesity and associated diseases." (PMID 32308702, 2020). "Nonetheless,it has been reviewed that gut microbiota causes obesity by affecting various variables like increase lipoprotein lipase action (LPL), host genome, lipogenesis, inflammation, expandedcalories, intestinal penetrability, consumption of food and use of energy." (PMID 32405173, 2020). "Since neuronal LPL deficiency is associated with improved glucose tolerance despite obesity, we reasoned that these animals may be more insulin sensitive." (PMID 32998280, 2020). "While we cannot rule out the significant effects of other regulating factors of the RCT system, it is clear that, in the setting of obesity and hyperlipidemia, LPL inhibition-mediated alterations are associated with an increased risk of metabolic complications." (PMID 31234537, 2019). "More research is needed to understand the functional significance of each PL species in disease progression, to assess whether PL and LPL metabolisms represent a promising target for the sex-dependent treatment of obesity-associated diseases." (PMID 30808418, 2019). "Since apoA5 protein and LPL proteins interact functionally to regulate lipid metabolism, and SNPs for each gene were associated with obesity risk, so evaluating gene combinations may be more effective than single SNP analyses in identifying genetic risk." (PMID 30053818, 2018). "Additionally, a study of postmenopausal women with overweight or obesity after a 6-month hypocaloric dietary intervention demonstrated that decreased LPL activity was associated with reductions in abdominal adiposity, total cholesterol, LDLs and TGs." (PMID 29075849, 2018). "Furthermore, adipose LPL expressions were decreased in sham-operated obese mice, but HV reversed the decreased adipose LPL expressions associated with obesity development, in both ob/ob and KK-Ay mice." (PMID 26268630, 2015). "As epigenetic alterations in AT may be associated with obesity-related phenotypes, we performed quantitative analysis of single CpG methylation within the LPL, ADIPOQ and PPARγ promoters." (PMID 26148147, 2015). "Moreover, hepatic LPL deficiency seems to protect against diet-induced obesity and hepatic steatosis in mice." (PMID 23110339, 2012). "During lipolytic reaction, LPL is a rate-limiting enzyme in the provision of free fatty acid to muscles (utilization) and the adipose tissue (storage), thereby leading to weight loss or obesity." (PMID 22330327, 2012).